RNU6-655P (RNA, U6 small nuclear 655, pseudogene)
Gene: Small nuclear RNA gene on chromosome 18 (78,036,739 to 78,036,845, forward strand). Ensembl gene ENSG00000199728.
Homologues: Orthologues: chimpanzee U6 (98% identical), macaque U6 (94% identical), mouse Gm26166 (87% identical), dog U6 (78% identical), pig U6 (76% identical), pig U6 (72% identical). Paralogues in human: RNU6-1152P (88% identical), RNU6-35P (88% identical), RNU6-41P (88% identical), RNU6-820P (88% identical), RNU6-1122P (87% identical), RNU6-12P (87% identical), RNU6-13P (87% identical), RNU6-166P (87% identical), RNU6-16P (87% identical), RNU6-175P (87% identical), RNU6-19P (87% identical), RNU6-24P (87% identical), and 1285 more.